IRF6 (interferon regulatory factor 6)
Diseases named in the same sentence as IRF6 in open-access papers (continued):
Sharing a sentence is not in itself a finding about the gene and the disease.
IRF6 also shares sentences with these, for which no sentence is quoted: cleft lip and palate (3 papers); prostate carcinoma (3); Branchio-oculo-facial syndrome (2); Hypodontia (2); hypospadias (2); pterygium (2); adenocarcinoma (1); age-related hearing loss (1); atherosclerosis (1); Blepharocheilodontic syndrome 2 (1); celiac disease (1); chronic kidney disease (1); CNS tumors (1); cocoon syndrome (1); colon cancer (1); dental anomaly (1); dental caries (1); ectodermal dysplasia (1); genetic disorders (1); Hay-Wells syndrome (1); Kallmann syndrome (1); keloid (1); Lewis lung carcinoma (1); lipoma (1); liver fibrosis (1); melanocytic nevus (1); metabolic disease (1); mucormycosis (1); multiple myeloma (1); nervous system tumor (1).
A further 10 diseases each share a sentence with IRF6 in 1 paper.